ENSG00000212378
Synonyms: LOC124900538
Gene: Small nucleolar RNA gene on chromosome 2 (72,760,534 to 72,760,602, forward strand). Ensembl gene ENSG00000212378.
Gene Ontology:
Biological process: RNA processing
Cellular component: nucleolus